MIR4444-2 (microRNA 4444-2)
Synonyms: hsa-mir-4444-2
Gene: MicroRNA gene on chromosome 3 (75,214,476 to 75,214,549, forward strand). Ensembl gene ENSG00000266780.
Homologues: Paralogues in human: MIR4444-1 (100% identical).